CRP (C-reactive protein)
Diseases named in the same sentence as CRP in open-access papers (continued):
Sharing a sentence is not in itself a finding about the gene and the disease.
Anosmia (16 papers, 2020 to 2025). An inability to perceive odors. "Group 1 exhibited statistically significant improvements in fever, cough, diarrhea, as well as NLR, IL-6, and CRP by 14 days, and in anosmia, loss of taste, shortness of breath, general weakness, and headache by 60 days." (PMID 39355453, 2024). "On the contrary, weakness (p = 0.02), cough (p = 0.01), ageusia (p = 0.02), anosmia (p = 0.03) and CRP>100 mg/L at admission (p<0.01) were associated with a long delay between symptom onset and hospital admission." (PMID 34995292, 2022). "In addition, anosmia was associated with lower adjusted values of D-dimer, CRP, and higher lymphocyte levels." (PMID 35053224, 2022). "For CT-confirmed ARS these are: 1) previous diagnosis of ARS; 2) preceding URTI; 3) anosmia; 4) double sickening; 5) purulent nasal discharge on examination; 6) need for antibiotics as judged by physician; and 7) CRP." (PMID 35817585, 2022). "Extended lung involvement of COVID-19 pneumonia can be predicted in clinics with patient's initial symptoms, vital signs, and laboratory tests, including anosmia, low SpO2, high RR, WBC, and CRP." (PMID 34794467, 2021). "We found that patients with anosmia, lower SpO2 (< 93), and higher respiratory rate (> 25 per minute), WBC count (> 10,000 cells/mm3), CRP (> 90 mg/Liter) had higher total CT scores." (PMID 34794467, 2021). "Taken together, we found that patients with anosmia, higher respiratory rate, WBC count, or CRP, and lower SpO2 had extended pulmonary involvement of COVID-19 pneumonia, which can cause adverse outcomes, including more extended hospitalization and recovery period." (PMID 34794467, 2021).
aortic aneurysm (16 papers, 2007 to 2025). A ruptured aneurysm located in the wall of the proximal portion of the descending aorta proceeding from the arch of the aorta. "Evidence suggests that interleukin-6 (IL6) signaling is causally associated with aortic aneurysm independently of the effect of C-reactive protein (CRP)." (PMID 34168680, 2021). "High serum CRP level was associated with stronger mCRP immunopositivity and a larger maximal diameter of aortic aneurysm." (PMID 34428207, 2021). "Various systemic laboratory diagnostic biomarkers have been investigated and linked to the risk for aortic aneurysm or its outcomes, such as CRP, Hcy and Cys-c." (PMID 30373522, 2018). "The decrease in the expression of these genes responsible for maintaining vessel diameter, vascular tone, and structural integrity in the high-CRP group suggests that CRP deposition is closely associated with the compromised vascular integrity observed in aortic aneurysms." (PMID 39737187, 2024). "One of the risk factors of aortic aneurysm development is the high CRP level." (PMID 35072395, 2022). "Previous studies showed that serum CRP levels were associated with large aortic aneurysm diameters." (PMID 34428207, 2021). "The maximal diameter of aortic aneurysms was 6.3 ± 1.5 cm in the high-CRP group and 5.8 ± 0.3 cm in the low-CRP group." (PMID 39737187, 2024). "One previous study reported higher serum CRP in IgG4-related aortic aneurysms and periaortitis compared with IgG4-related retroperitoneal fibrosis." (PMID 33348892, 2020). "CRP and D-dimer are systemic laboratory diagnostic biomarkers have been investigated and linked to the risk for aortic aneurysms or its outcomes but not sensitive and specific enough in clinical application." (PMID 37378402, 2023). "Above evidence might explain our findings that serum MMP9 levels were positively correlated with circulating CRP and Hcy, which could partly reflect the fact that multiple biomarkers responded to aortic aneurysm related events." (PMID 30373522, 2018). "and these agents might suppress the inflammatory process.Besides these findings, extensive inflammation including medialand adventitial cell infiltrations was observed in postmortem examination of aorticaneurysm, and higher serum CRP levels were observed inasymptomatic aortic aneurysm persons." (PMID 17497040, 2007). "C-reactive protein and creatinine levels were not dramatically different among the three aortic aneurysm groups." (PMID 31664168, 2019). "To date, circulating biomarkers, such as C-reactive protein (CRP), homocysteine (Hcy) and Cystatin C (Cys-c), have been analyzed in aortic aneurysmal diseases, but it remains unclear whether the studied biomarkers are correlated with serum MMP9." (PMID 30373522, 2018). "However, the authors reported that this correlation was non-specific, as CRP was also elevated in patients with coronary plaques, aortic aneurysms, and failed coronary bypasses." (PMID 36582735, 2022).
calcification (16 papers, 2010 to 2025). Process by which organic tissue becomes hardened by the physiologic deposit of calcium salts. "Pro inflammatory cytokines are elevated, with C-reactive protein (CRP) associated with coronary calcification in children, and interleukin-6 (IL-6) and CRP associated with CV mortality in adults." (PMID 36114889, 2023). "Statin treatment over 2 years associated with a significant increase in coronary calcification in patients with higher systemic inflammation, as measured by hs‐CRP." (PMID 35366378, 2022). "Increased C-reactive protein (CRP), which is a predictor of cardiovascular risk factors and death in the general population, has been long associated with increased vascular calcification and mortality in hemodialysis patients." (PMID 31241466, 2019). "In RA increased vascular calcification has been noted and found to be associated with CRP levels." (PMID 28400572, 2017). "Age and HD vintage, PTH and CRP are significant factors of coronary calcifications on the bivariate analysis while regression analysis selected Age and HD age." (PMID 20565936, 2010). "Thus, in complex pathological conditions such as CKD, elevated systemic CRP levels as well as locally produced CRP may directly contribute to the progression of vascular calcification." (PMID 31377747, 2019). "CCA-IMT and the presence of plaques in common carotid artery were positive predictors of radial artery calcifications, independent of dialysis status, Framingham risk score, CRP and Ca x Pi [OR for calcifications 2.19 (1.08-4.45) per 0.1 mm increase in CCA-IMT]." (PMID 26037625, 2015). "Although, previous data do not support a significant correlation of coronary calcification and CRP levels in CABG patients, a subgroup analysis in statin-free patients found a clear correlation." (PMID 32685095, 2020).
complication (16 papers, 2014 to 2025). Any disease or disorder that occurs during the course of, or because of, another disease, treatment, or procedure. "In the present analysis incidence of biliary complications despite PTBD was independent of CRP and BMI, but both higher CRP and lower BMI were associated with increased mortality following PTBD." (PMID 39500762, 2025). "The NIHSS, SEDAN score, THRIVE score, mRS, and leukocyte and CRP values were found to be statistically significantly higher in female patients who developed CNS complications (n = 71, 9.7%) (p = 0.001; p = 0.001; p = 0.001; p = 0.001; p = 0.005; p = 0.015, respectively)." (PMID 35401392, 2022). "Current smokers had a higher risk of pleural complications independent of CRP levels, the presence of pleuritic pain, and a higher platelet count." (PMID 32906593, 2020). "Although no research related to the association between AIM2 methylation and diabetic vascular complications was found, AIM2 methylation level changes could affect the relationship between C-reactive protein and traumatic stress disorder." (PMID 30555415, 2018). "The EURODIAB Prospective Complication Study hypothesized that a Z-score composed by C-reactive protein (CRP), Tumor Necrosis Factor-α (TNF-α), and interleukin-6 (IL-6) could be associated with the presence of vascular complications in diabetic patients." (PMID 27376090, 2016).
dermatitis (16 papers, 2019 to 2025). An inflammatory process affecting the skin. "Elevated levels of inflammatory mediators like TNF-α, IL-8, IL-6, IL-1β, and C-reactive protein (CRP) contribute to skin inflammation and immune-related skin disorders." (PMID 41179869, 2025). "Skin disorders, pruritus, and fatigue tended to be more frequent in the CRP-low compared to the CRP-high group." (PMID 38730675, 2024). "CRP is a biomarker and measures systemic inflammation, and our study finding is in line with a previous report that showed that patients with flaky paint dermatosis had lowered TRP levels and enhanced activity of IDO because of increased CRP levels." (PMID 35565678, 2022). "The DII is correlated with inflammatory biomarkers such as C-reactive protein (CRP), interleukin (IL)-6, and tumor necrosis factor (TNF)-α in various ethnic groups, and those inflammatory biomarkers contribute to the development and progression of dermatitis." (PMID 39464683, 2024).
kidney stones (16 papers, 2014 to 2026). "Another study (NHANES 2007–2014) reported a significant association between CRP levels and lifetime kidney stone prevalence across all age groups." (PMID 40075397, 2025). "A previous study indicated that the biomarkers C-reactive protein and erythrocyte sedimentation rate are closely associated with kidney stones." (PMID 40162317, 2025). "CRP is another common inflammatory marker, and higher levels of CRP are significantly associated with an increased prevalence of kidney stones." (PMID 40162317, 2025). "A study employing data from the NHANES 2007–2009 revealed a significant association between elevated CRP levels (3rd to 5th quintile) and the prevalence of kidney stones in individuals aged 20–39 years." (PMID 40075397, 2025). "Participants in the highest CRP quartile experienced a 69% increased risk of kidney stones compared to those in the lowest quartile (OR = 1.64, 95% CI: 1.04–2.59, p = 0.03)." (PMID 38281018, 2024). "CRP was positively associated with the risk of kidney stones (Model 1: OR = 1.09, 95% CI: 1.01–1.18, p = 0.03; Model 2: OR = 1.09, 95% CI: 1.00–1.18, p = 0.03, Model 3: OR = 1.14, 95%CI: 1.02–1.26, p = 0.04)." (PMID 38281018, 2024). "In our current investigation, CRP emerges as a promising biomarker for identifying the risk of kidney stones." (PMID 38281018, 2024). "Our findings reveal a significant association between higher CRP levels and an increased risk of kidney stones." (PMID 38281018, 2024). "Primarily, the cross-sectional design of our study precludes establishing a causal relationship between C-reactive protein (CRP) and the risk of kidney stones." (PMID 38281018, 2024). "The relationship between C-reactive protein (CRP) and the risk of developing kidney stones is unclear, and we aimed to assess the association between CRP and kidney stones in US adults." (PMID 38281018, 2024). "Our study demonstrated that increased CRP levels were associated with an elevated likelihood of kidney stones." (PMID 38281018, 2024). "A positive association was observed between CRP and the risk of kidney stones (OR = 1.09, 95% CI: 1.01–1.18, p = 0.03) in the unadjusted model." (PMID 38281018, 2024). "In this large cross-sectional study including 11,033 US adults, we found a positive association between CRP levels and the risk of kidney stones in unadjusted models and in models adjusted for age, gender, race and educational levels." (PMID 38281018, 2024). "Elevated CRP levels are a well-known risk factor for cardiovascular events, and have also been associated with kidney stones." (PMID 29757578, 2018). "A study based on NHANES data from 2007 to 2014 revealed that a neutrophil-to-lymphocyte ratio (NLR) greater than 1.72 was associated with an increased prevalence of kidney stones and a greater number of stones passed, indicating the relevance of inflammatory markers other than CRP in this condition." (PMID 40075397, 2025). "Higher CRP levels were associated with a higher incidence of kidney stones." (PMID 38281018, 2024). "The precise mechanism underlying the positive association between CRP and kidney stones remains unclear." (PMID 38281018, 2024). "In clinical practice, heightened awareness of CRP as a potential biomarker could aid in risk assessment and management strategies for kidney stone patients." (PMID 38281018, 2024). "This suggested that the levels of CRP increased the risk of developing kidney stones." (PMID 38281018, 2024). "Hence, our investigation aimed to determine whether there exists a correlation between CRP levels and the risk of developing kidney stones." (PMID 38281018, 2024). "For example, elevated serum levels of the inflammatory marker C-reactive protein (CRP) have been reported in patients with kidney stones." (PMID 40944726, 2025). "In conclusion, our finding from this study suggested that clinicians should focus on CRP levels in patients with kidney stones." (PMID 38281018, 2024).
kidney stones (continued). "Previous studies suggested that some serum and urine parameters are predictors of kidney stones, including the urinary sodium/potassium ratio, serum calcium, 25-hydroxyvitamin D (25OHD), C-reactive protein (CRP), urate, testosterone, estradiol, and lipids." (PMID 37810889, 2023). "Several inflammatory biomarkers [e.g., c-reactive protein (CRP), P-selectin] usually increase in the urine of individuals with kidney stones." (PMID 36313098, 2022). "Notably, participants in Quartile 4 of CRP exhibited a higher prevalence of kidney stones (10.89%, p = 0.01) compared to Quartiles 1–3." (PMID 38281018, 2024). "This information could have provided valuable insights into the interplay between CRP and kidney stones in a more defined subgroup." (PMID 38281018, 2024). "Additionally, the absence of data on the components of kidney stones precluded a more in-depth analysis of the relationship between CRP and specific types of kidney stones." (PMID 38281018, 2024). "Notably, as CRP levels increased, the prevalence of kidney stones exhibited a corresponding rise across quartiles (Kidney stones: Quartile 1: 7.59%; Quartile 2: 8.77%; Quartile 3: 9.64%; Quartile 4: 10.89%)." (PMID 38281018, 2024). "Finally, we included a total of 11,033 participants and performed weighted multivariate regression analysis and subgroup analysis to assess the independent relationship between CRP and kidney stones." (PMID 38281018, 2024). "Notably, elevated levels of C-reactive protein (CRP) and a high neutrophil-to-lymphocyte ratio (NLR) have been correlated with an increased incidence of kidney stones." (PMID 40075397, 2025). "We used data from NHANES 2007–2010, and we excluded participants who were under 18 years of age and lacked data on CRP and kidney stones." (PMID 38281018, 2024). "A study concluded that there exists a notable relationship between serum CRP and self-reported kidney stones in youth, and another study found that significantly increased CRP is a predictive factor for spontaneous stone non-passage in cases with 4–8 mm distal ureteral stones." (PMID 37873776, 2023). "It is not clear yet whether the increase of CRP in nephrolithiasis patients is related to the presence of septic complications or is an effect of surgical-related trauma itself." (PMID 25722986, 2015).
pancreatic ductal adenocarcinoma (16 papers, 2016 to 2026). An infiltrating adenocarcinoma that arises from the epithelial cells of the pancreas. "Emerging evidence indicates that an elevated C-reactive protein-to-albumin ratio (CAR) may be associated with a poor prognosis in pancreatic ductal adenocarcinoma (PDAC)." (PMID 33028394, 2020). "Another study reported that the combined use of CA19-9 and C-reactive protein (CRP) levels is a novel prognostic strategy for pancreatic ductal adenocarcinoma." (PMID 39857647, 2024). "Two days after the procedure with antibiotics, his CRP level decreased abruptly, and he received chemotherapy for the treatment of pancreatic ductal adenocarcinoma (PDAC) 5 days after the procedure." (PMID 33879679, 2021). "PURPOSE: This study aimed to investigate the prognostic impact of preoperative indicators that reflect systemic inflammatory, nutritional, and immune status, focusing on the C-reactive protein–albumin–lymphocyte (CALLY) index in patients undergoing surgery for pancreatic ductal adenocarcinoma." (PMID 41854738, 2026). "In this large retrospective study, we show that in surgically treated pancreatic ductal adenocarcinoma (PDAC), preoperatively increased levels of plasma CRP independently predict worse postoperative prognosis." (PMID 27632196, 2016). "Rectus abdominis muscle biopsies were collected during surgery of patients with pancreatic ductal adenocarcinoma (n = 10 without cachexia, n = 20 cachectic without inflammation (CRP < 10 mg/L), n = 10 cachectic with inflammation (CRP ≥ 10 mg/L)." (PMID 38725139, 2024). "We examined whether elevated plasma C-reactive protein (CRP), carbohydrate antigen (CA) 19-9, interleukin-6 (IL-6) and YKL-40, individually or combined, can identify poor survivors among patients with pancreatic ductal adenocarcinoma (PDAC)." (PMID 34572824, 2021).
prostatitis (16 papers, 2013 to 2025). An infectious or non-infectious inflammatory process affecting the prostate gland. "Serum biomarkers, such as prostate-specific arginine esterase and CRP, have been explored; however, their diagnostic performance remains inconsistent, with CRP demonstrating limited utility in distinguishing BPH from other prostatic diseases." (PMID 40689176, 2025).
pulmonary edema (16 papers, 2010 to 2024). Accumulation of fluid in the lung tissues causing disturbance of the gas exchange that may lead to respiratory failure. "Furthermore, C-reactive protein (CRP) increases are associated with the development of pulmonary edema." (PMID 23690660, 2013). "The aim of this study was to determine the diagnostic utility of combination measurements of BNP and C-reactive protein (CRP) in critically ill patients with pulmonary edema." (PMID 21696613, 2011). "However, in previous studies CRP had value in differentiating ARDS from cardiogenic pulmonary edema and the CRP and LIS decline upon successful ARDS treatment by corticosteroids." (PMID 25888398, 2015). "Finally, a high postoperative CRP level may be a risk factor for noncardiogenic pulmonary edema in the vasospasm period." (PMID 24818154, 2014). "This is the first report evaluating the utility of measuring both CRP and BNP in plasma to provide a differential diagnosis in patients with pulmonary edema." (PMID 21696613, 2011). "Although the possibility of a concomitant lung infection is present, as evidenced by increased inflammatory markers on admission (CRP and procalcitonin), it would not explain the whole clinical picture of severe pulmonary edema." (PMID 39224493, 2024). "In conclusion, clipping affects postoperative CRP level and may thereby increase noncardiogenic pulmonary edema in the vasospasm period." (PMID 24818154, 2014). "In this study, we found two types of pulmonary edema after SAH: cardiogenic pulmonary edema due to poor cardiac contractility in the early period and noncardiac pulmonary edema due to elevation of the postoperative CRP level, which mainly occurred after clipping." (PMID 24818154, 2014).